EGFR (epidermal growth factor receptor)
Diseases named in the same sentence as EGFR in open-access papers (continued):
Sharing a sentence is not in itself a finding about the gene and the disease.
glioblastoma (continued). "We also found that RhoG is activated by cMet and EGFR, two receptors that are deregulated in glioblastoma tumors, further underlining the relevance of RhoG-mediated signaling in the context of glioblastoma." (PMID 22966858, 2012). "Another study demonstrated that rapamycin enhanced the sensitivity of Pten-deficient glioblastoma cells to treatment with the EGFR inhibitor erlotinib." (PMID 23139750, 2012). "Elimination of EGFR amplification during glioblastoma cells culturing is a well-known phenomenon the causes of which, however, remain enigmatic." (PMID 21326241, 2011). "Recent reports have shown that EGFR mutations are rare or occur at a very low frequency in acute leukaemia, glioblastoma, and colorectal, gastric, breast, and hepatocellular carcinomas." (PMID 21730982, 2011). "A directed RNAi screen revealed that glioblastoma cells over-expressing EGFRvIII, an oncogenic variant of EGFR, become hyper-dependent on a variety of DNA repair genes." (PMID 20532243, 2010). "An in-frame deletion of exon 2-7 of EGFR is frequently detected in glioblastoma, which encodes a constitutively active EGFR protein." (PMID 20828404, 2010). "For instance, while EGFR mutations or copy number alterations are found in nearly 50% of all glioblastomas, EGFR inhibition has yet to yield significant improvements in clinical outcome." (PMID 20532243, 2010). "The majority of the glioblastoma cases are primary glioblastomas, hence developed de novo displaying aberrations in the EGFR expression, p16INK4a, and PTEN mutations." (PMID 19558675, 2009). "Similar evidence was reported in glioblastomas, where the variant form of EGFR gene frequently demonstrates allele-specific amplification." (PMID 19889201, 2009). "Glioblastoma datasets from The Cancer Genome Atlas were analyzed for alterations in EGFR, PDGFRA and NF1 and the possible association of mutations in these genes with transcriptomally-defined subclasses." (PMID 19915670, 2009). "This suggests loss of several features of glioblastoma aggressiveness in BTL3 probably based on lower EGFR-mediated signals." (PMID 17342095, 2007). "EGFR mutations have been demonstrated with a high frequency in glioblastomas with the majority of these tumors demonstrating increased expression of EGFR and a subset showing expression of the common deletion mutation EGFRvIII." (PMID 17437646, 2007). "The overexpression of EGFR mRNA, caused by amplification of the erbB-1 gene, has been observed in approximately 40–50% of human glioblastomas." (PMID 15305185, 2004). "Interestingly, a common EGFR mutation found in glioblastoma—the de2-7EGFR truncation (EGFRvIII)—disrupts Cys295-Cys307 cysteine pairing due to the absence of Cys295." (PMID 40298862, 2025). "These disappointing results were likely dependent on the mechanism of action of erlotinib and gefitinib, which were designed to target the intracellular tyrosine kinase domain, while the most frequent EGFR mutations in glioblastoma affect the extracellular domain." (PMID 40332381, 2025). "EVs derived from glioblastoma cells carrying mutant epidermal growth factor receptor (EGFR) variant III (EGFRvIII) transcripts were found to stimulate tubule formation in ex vivo angiogenesis assays, although the role of EGFRvIII was not explicitly documented in this setting." (PMID 40563616, 2025). "Rapid early progression was associated with presence of EGFR alterations in glioblastoma." (PMID 41212363, 2025). "The choice of EGFR as a target was due to the high expression of this receptor in a primary glioblastoma (observed in 60% of patients, EGFRvIII mutation in 50% of patients), as well as the known negative effect of this biomarker on the prognosis of the disease." (PMID 41473440, 2025).
glioblastoma (continued). "Similarly, novel EGFR inhibitors and EGFRvIII-targeted therapies such as vaccines are actively being studied as EGFR, which is frequently overexpressed or mutated in glioblastoma, drives tumor proliferation and resistance." (PMID 39982223, 2025). "Notably, EGFRvIII has been extensively characterized in glioblastoma, where it is associated with aggressive tumor behavior and reduced responses to EGFR-targeted therapies." (PMID 40472740, 2025). "Mutations in EGFR, particularly the vIII variant, are present in over half of glioblastoma cases." (PMID 40940872, 2025). "EGFR mutation and expression are crucial in drug efficacy for treating glioblastoma." (PMID 40564017, 2025). "Notably, half of all glioblastomas multiforme (GBMs), which share many characteristics with NSCs, overexpress EGFR or have activating mutations with the EGFR coding sequence." (PMID 40593476, 2025). "EGFR is the most frequently mutated protein in human glioblastoma." (PMID 40332381, 2025). "EGFR mutations are over-expressed in glioblastoma tumors (50–60% of the time)." (PMID 40564017, 2025). "Amplification of EGFR is the most common genetic alteration that occurs in glioblastoma, and glioblastoma shows that amplified EGFR commonly overexpresses the receptor variant III (EGFRvIII), which indicates the importance of EGFRvIII in the case of elevated proliferation of glioma cells." (PMID 40732344, 2025). "Sixty-three percent of the patients (n = 35/54) could be conclusively reclassified as glioblastoma based on either TERT mutation or EGFR amplification or both (n = 4/35)." (PMID 38672254, 2024). "Various EGFR variants have been associated with glioblastoma." (PMID 38396993, 2024). "Mis-sense mutations of EGFR ECD constitute about 10% of glioblastoma cases." (PMID 38396993, 2024). "The overall discrepancy between our pre-clinical data and the reported clinical trials could be a consequence of glioblastoma heterogeneity, of the rapid development of resistance, as well as the sub-clonal nature of EGFR mutations in glioblastoma." (PMID 38548752, 2024). "Overall, MGMT methylation was seen in 35% (n = 8), IDH mutations were observed in 35% (n = 8, all grade III), and EGFR amplification was seen in 44% (n = 10, all glioblastoma) of patients, consistent with the heterogenous population of malignant glioma patients." (PMID 38719809, 2024). "In glioblastoma, both EGFR gene amplification and mutations have been described." (PMID 39273661, 2024). "In addition, amplifying the epidermal growth factor receptor (EGFR) gene represents another pivotal genetic modification linked to CIN in IDH wildtype glioblastoma." (PMID 39227895, 2024). "Tumors with a TERT mutation and/or EGFR amplification were reclassified as glioblastoma." (PMID 38672254, 2024). "Furthermore, EGFR amplifications have been linked to various primary tumors of the nervous system, such as glioblastoma and oligodendrogliomas." (PMID 38505421, 2024). "For example, Pyruvate kinase M2 (PKM2) translocates into the nucleus in epidermal growth factor receptor (EGFR) activated glioblastoma cells, where it associates with β-Catenin to facilitate its recruitment to the CCND1 promoter, leading to tumor cell proliferation and brain tumor development." (PMID 38351096, 2024).
glioblastoma (continued). "EGFR (Epidermal Growth Factor Receptor) expression, a cell membrane tyrosine kinase receptor, has been implicated in several mechanisms contributing to the abnormal and swift cell proliferation observed in various CNS tumors including glioblastomas." (PMID 39375809, 2024). "The Glioblastoma-EV-mediated release of EGFR mutant/variant III (EGFRvIII) in the context of CD9 tetraspanin may enhance glioblastoma progression, including cell invasion and angiogenesis." (PMID 38379858, 2024). "Additionally, wildtype EGFR amplification is observed in 57.4% of glioblastoma cases, and it concurrently associates with each of these variants." (PMID 38396993, 2024). "EGFR amplification and mutations are frequent events in Glioblastoma Multiforme (GBM)." (PMID 39130636, 2024). "Moreover, the upregulation of c-MET has been found after EGFR monotherapy in glioblastoma stem cells (GSCs) in vitro, causing long-term self-renewal ability in these cells." (PMID 39272879, 2024). "For example, in glioblastoma, cancer cells modulate expression levels of the oncogenic variant EGFRvIII to optimize growth and response to epidermal growth factor receptor tyrosine kinase inhibitors (EGFR-TKIs)." (PMID 39202666, 2024). "In this study, we investigated whether mutations in the EGFR gene in glioblastoma lead to lipid metabolic-dependent phenotypes in response to the blood–brain barrier penetrant drug BAY2402234." (PMID 39195509, 2024). "Notably, it is the most prevalent variant found in glioblastomas and when it co-occurs with amplified EGFR, it results in a poor prognosis." (PMID 38396993, 2024). "40–60% of glioblastomas carry mutations or increased copy numbers of the EGFR gene." (PMID 38638676, 2024). "In a preclinical study, osimertinib also showed marked efficacy in EGFR-mutated glioblastoma." (PMID 36980614, 2023). "Interestingly, in glioblastoma, it has been reported that the presence of EGFRvIII is associated with EGFR gene amplification in most cases." (PMID 36622089, 2023). "Kim discovered that in glioblastoma, the epidermal growth factor receptor (EGFR) gene was frequently mutated to EGFRvIII, which could offer tumor cells an advantage in terms of proliferation." (PMID 37337170, 2023). "In addition, because the activation of the EGFR pathway has been previously linked to altered metabolic processes, including the “lipogenic phenotype” in glioblastoma multiforme, we investigated the effect of EGF treatment in these cells." (PMID 36732018, 2023). "Glioblastoma frequently has epidermal growth factor receptor (EGFR) mutations." (PMID 37509607, 2023). "However, there was a study on CAR NK cells transduced with bispecific CAR constructs as a solution to antigen loss in EGFRvIII-directed CAR NK cell therapy for glioblastoma, targeting both mutated and wild-type EGFR." (PMID 37165457, 2023). "In glioblastoma, the most frequently (~30%) occurring EGFR mutation is EGFRΔIII (EGFR variant III), which results from the in-frame deletion of 801 base pairs spanning exons 2–7 of the coding sequence, resulting in ligand-independent activation of EGFR tyrosine kinase activity." (PMID 38201251, 2023).
glioblastoma (continued). "EGFR is amplified, mutated or both in 40% of primary glioblastomas." (PMID 37046685, 2023). "For example, increased EGFR expression is associated with increased tumor chemoresistance and radioresistance in tumors, including squamous cell carcinoma, ovarian adenocarcinoma, hepatocarcinoma, glioblastoma, and adenosquamous carcinoma of the cervix." (PMID 38026933, 2023). "Thus, glioblastoma organoids were found to be sensitive to gefitinib in EGFR mutation presence; to trametinib, in tumors with NF1 mutation, to everolimus, in tumors with PI3K mutation." (PMID 38435477, 2023). "It is the most common EGFR mutation occurring in glioblastoma." (PMID 38201251, 2023). "The team found that glioblastoma cells can develop resistance to the epidermal growth factor receptor (EGFR) -targeting drug erlotinib by eliminating an extrachromosomal copy of the mutated EGFR gene." (PMID 38027570, 2023). "EGFRvIII is associated with EGFR amplification in 30–40% of glioblastoma cases, and the expression of EGFRvIII is a negative prognostic marker for the overall survival in patients with glioblastoma surviving at least 1 year long." (PMID 38201434, 2023). "Research conducted in Mischel's laboratory unveiled that resistance to epidermal growth factor receptor (EGFR) inhibitors in glioblastoma could be attributed to the reversible loss of EGFRvIII gain-of-function mutations on eccDNA." (PMID 39534571, 2023). "More than 50% of glioblastomas with EGFR amplification also contain the EGFRvIII gene mutation, which is characterized by the deletion of exons 2 to 7, resulting in a sense mutation with a truncated extracellular domain and ligand-independent constitutive activity." (PMID 35693015, 2022). "In addition, diffuse astrocytoma, if accompanied by microvascular proliferation or necrosis or TERT promoter mutation or EGFR gene amplification or + 7/-10 chromosome copy number changes, will also be included in glioblastoma, IDH wild type category." (PMID 35241019, 2022). "For example, the epidermal growth factor receptor (EGFR), which has been implicated in glioma development, is frequently amplified, mutated, and overexpressed in malignant gliomas, especially glioblastoma." (PMID 36267281, 2022). "Interestingly, although this EGFR variant reinforces tumor growth and migration, it seems to be a favorite prognostic marker, since overall survival of glioblastoma patients upon administration of the standard RCT is increased." (PMID 35626024, 2022). "EGFR amplification and/or mutation are found in more than half of the cases with glioblastoma." (PMID 35521558, 2022). "In particular, the EGFR variant III (EGFRvIII) with a deletion of exons 2–7 in glioblastoma, which is frequently co-expressed with the wild-type receptor (wtEGFR) in association with STAT-3, plays a key role in the resistance of cancer cells to chemotherapy and radiotherapy." (PMID 36499115, 2022). "In glioblastoma, a particular group of EGFR deletions and point mutations are frequently found." (PMID 35911278, 2022). "In glioblastoma, EGFR is frequently mutated, forming the oncogenic variant EGFRvIII." (PMID 35844796, 2022). "Interestingly, a similar mechanism has been observed with EGFR ECD mutations in glioblastoma, where missense mutations located at the domain I-to-II interface led to spontaneous untethering of the self-inhibitory tether driving oncogenicity." (PMID 35409179, 2022). "The mutation present in EGFRvIII cells is characteristic of GBM since 40% of glioblastoma cells have a mutation that overexpresses EGFR, of which about 50% is the EGFRvIII variant, which results in uninterrupted activity of the receptor without the need for external stimulation." (PMID 35055109, 2022).
glioblastoma (continued). "Vaccination of glioblastoma patients with a peptide mimicking the EGFR variant III (EGFRvIII) in glioblastoma cells, together with standard temozolomide chemotherapy or the anti-angiogenic agent bevacizumab, showed promising anti-glioblastoma effects in clinical trials." (PMID 33572835, 2021). "On the other hand, tumours with overexpression or activating mutations in EGFR, such as carcinomas of the upper gastrointestinal tract, lung and mammary tissue, or glioblastomas, might be responsive to impairment of RAL function." (PMID 34096503, 2021). "Amplification and mutation of the EGFR gene are often seen in primary glioblastoma cells." (PMID 34338396, 2021). "Of the four predicted IDH-wildtype glioblastoma patients that lived longer than three years, two harbored hallmark + 7/ − 10 and EGFR amplification as well as co-gain of chromosomes 19 and 20, a documented marker for long-term survivors in IDH-wildtype glioblastoma." (PMID 34863298, 2021). "Glioblastomas are characterized by extensive genetic alterations, including amplification of the gene encoding the epidermal growth factor receptor (EGFR) and inactivating the mutation or deletion of Phosphatase and Tensin homolog deleted on chromosome 10 (PTEN), both promoting invasive behavior." (PMID 34830972, 2021). "The increased expression level of GBP1 was associated with EGFR amplification in glioblastoma multiforme patients with poor prognosis, implying that EGFR signaling might also be required for GBP5 induction in OSCC." (PMID 34439200, 2021). "An abnormal alteration in EGFR expression and activation can transform a healthy cell into a cancerous cell, and this is a hallmark of many types of epithelial carcinomas such as breast, lung, renal, or head and neck cancer and glioblastoma." (PMID 34943898, 2021). "In addition, our study discovered a novel interaction of Lpd with RICTOR, a regulator of glioblastoma radiosensitivity and chemoresistance in tumors with mutated EGFR by facilitating NFκB signaling." (PMID 34771501, 2021). "Verteporfin has been evaluated in clinical trials of various cancer types, including cutaneous metastatic breast cancer, and in vitro and in vivo experiments in human glioblastoma stem cells and xenograft models identified verteporfin as a therapeutic candidate in EGFR-variant glioblastoma." (PMID 34771636, 2021). "A limitation of the previously published tools profiled in this study, beyond core performance metrics, is the lack of ability to detect clinically relevant single gene events, such as the EGFR vIII transcript variant that is a relatively frequent event in glioblastomas." (PMID 34745213, 2021). "TCGA has grouped glioblastomas relying on proteomic data into three classes: one showing epidermal growth factor receptor (EGFR) mutations or amplifications, the second having ligand-driven platelet-derived growth factor (PDGF) activation, and the third with a loss of RAS regulator, NF1." (PMID 34884508, 2021). "This microfluidic chip labeled with magnetic nanosensorsquantifies an EV-specific protein marker (CD63) and glioblastoma-specific proteins, such asepidermal growth factor receptor (EGFR) and EGFR variant III, on the surface of EVs viamicronuclear magnetic resonance (μNMR)." (PMID 39703905, 2021). "IDH-wildtype astrocytic gliomas with a glioblastoma classification (n = 9), presented typical chromosomal changes (EGFR amplification, chromosome 7 gain or chromosome 10 loss) and prognosis of glioblastoma with the exception of the case classified as glioblastoma IDH-wildtype, midline." (PMID 33941250, 2021). "An investigation on the nature of these therapeutic targets revealed a high diversity: Compounds directed against VEGF or the VEGFR were most frequently found, but there were also molecules directed against EGFR—a molecule prototypically mutated in subsets of adult glioblastoma." (PMID 34234357, 2021).